ARR3 (arrestin 3)
Description:
May play a role in an as yet undefined retina-specific signal transduction. Could bind to photoactivated-phosphorylated red/green opsins.
Synonyms: cArr; ARRX; MYP26
Tractability: No criterion of Open Targets' tractability assessment is met for any kind of drug.
Gene: Protein-coding gene on chromosome X (70,268,305 to 70,281,840, forward strand). Ensembl gene ENSG00000120500.
Subcellular location: Photoreceptor inner segment; Cell projection, cilium, photoreceptor outer segment
Subcellular location (Human Protein Atlas): Golgi apparatus; Vesicles
Gene Ontology:
Molecular function: protein binding; G protein-coupled receptor binding; opsin binding; phosphoprotein binding
Biological process: G protein-coupled receptor internalization; signal transduction; visual perception
Cellular component: photoreceptor inner segment; cytoplasm; photoreceptor outer segment; synapse
Homologues: Orthologues: chimpanzee ARR3 (99% identical), macaque ARR3 (97% identical), pig ARR3 (87% identical), dog ARR3 (86% identical), rabbit ARR3 (81% identical), mouse Arr3 (81% identical), rat Arr3 (78% identical), tropical clawed frog arr3 (64% identical), zebrafish arr3a (54% identical), zebrafish arr3b (49% identical), Drosophila melanogaster krz (47% identical), Caenorhabditis elegans arr-1 (45% identical). Paralogues in human: ARRB1 (60% identical), ARRB2 (55% identical), SAG (49% identical).
Diseases named in the same sentence as ARR3 in open-access papers:
ARR3 is named in the same sentence as 26 diseases in open-access papers, as found by Europe PMC text mining. Sharing a sentence is not in itself a finding about the gene and the disease. The quoted sentences say what the papers report.
myopia (16 papers, 2021 to 2026). "Compared to other non-syndromic myopia-associated genes, ARR3 exhibits several distinct characteristics." (PMID 40134578, 2025). "Recent studies have identified specific mutations in ARR3 that correlate with an elevated risk of myopia development, highlighting its potential involvement in the disease’s pathogenesis." (PMID 40134578, 2025). "This review summarizes current advancements in elucidating the relationship between ARR3 and myopia, emphasizing genetic variations associated with refractive errors and their implications for myopia research and clinical management." (PMID 40134578, 2025). "Recent study by Barboni, have provided empirical evidence for this dysfunction in myopia associated with ARR3." (PMID 40134578, 2025). "That same year, Yuan reported a male patient from Southern China with hemizygous ARR3 mutation (ARR3: c.569C>G, p.S190*) associated with high myopia." (PMID 40134578, 2025). "We identified a pathogenic variant in the ARR3 gene occurring in female siblings, a variant previously reported in female myopia patients in two large families." (PMID 39495751, 2024). "Variants of ARR3 reportedly cause X-linked dominant female-limited early-onset (age < 7 years old) high myopia (< − 6D)." (PMID 37268727, 2023). "X-linked myopia 26 caused by the variants of ARR3 is characterized by female-limited early-onset high myopia." (PMID 36769483, 2023). "The mosaic expression of normal or mutated ARR3 in cones lead to unbalanced cone function that results in higher visual contrast than naturally light input, thereby influencing the severity of myopia and visual acuity loss." (PMID 37268727, 2023). "Myopia due to ARR3 mutations is transmitted in X-linked female-limited inheritance, manifests with mild cone impairment and slowly progresses to pathologic myopia." (PMID 36180177, 2023). "Although the mode of inheritance of the eo-HM family fits the X-linked pattern of ARR3, the phenotypes of three patients deviate from the typical early-onset high myopia." (PMID 36769483, 2023). "In this study we describe three Caucasian multigenerational families with early onset high myopia with an X‐linked female‐limited inheritance pattern caused by a mutation in the ARR3 gene." (PMID 35001458, 2022). "We identified three Caucasian families with high myopia caused by three different pathogenic variants in the ARR3 gene (c.214C>T, p.Arg72*; c.767+1G>A; p.?; c.848delG, p.(Gly283fs))." (PMID 35001458, 2022). "This study describes the clinical spectrum and genetic background of high myopia caused by mutations in the ARR3 gene." (PMID 35001458, 2022). "In summary, mutations in the ARR3 gene should be considered in patients with early onset high myopia, especially in families with an X‐linked female limited inheritance pattern." (PMID 35001458, 2022). "Further in depth molecular studies on Arrestin‐3 dysfunction and its role in myopisation are required for complete understanding of how a pathogenic mutation in ARR3 can cause the myopia phenotype, limited to females." (PMID 35001458, 2022). "The myopia phenotype in carriers of this ARR3 variant was characterized by an early onset (<6 years), a progressive nature and a moderate to bad response to atropine treatment." (PMID 35001458, 2022). "We identified three Caucasian families with high myopia caused by a pathogenic variant in the ARR3 gene." (PMID 35001458, 2022). "To conclude, we identified three families with early onset, therapy‐resistant, high myopia with a female‐limited inheritance pattern, caused by a mutation in the ARR3 gene." (PMID 35001458, 2022). "Using whole exome sequencing, we identified the pathogenic mutation of the female-limited early onset high myopia observed in our patients to be a premature stop codon in the ARR3 gene." (PMID 33482870, 2021). "This is the first report of a mutation in ARR3 causing hereditary eoHM, called Myopia-26 in a Caucasian family." (PMID 33482870, 2021).
myopia (continued). "Overview of ARR3 gene mutations identified in early-onset high myopia research." (PMID 40134578, 2025). "Mutations in ARR3, which disrupt LM cone functionality, may enhance their sensitivity, fostering greater accommodative responses and providing a foundation for myopia onset." (PMID 40134578, 2025). "Notably, arrestin-C (ARR3), a gene associated explicitly with cone photoreceptors, has been identified as a significant marker for high myopia in humans." (PMID 40736176, 2025). "In 2016, Xiao identified ARR3 gene variants associated with female-limited early-onset high myopia (Myopia 26), demonstrating a sex-limited inheritance pattern where heterozygous females are primarily affected, while hemizygous males generally remain unaffected or exhibit only mild symptoms." (PMID 40134578, 2025). "Since ARR3 was first identified as a causative gene for early-onset high myopia in 2016, growing research has revealed its strong association with myopia, positioning it as one of the most prevalent myopia-related pathogenic genes." (PMID 40134578, 2025). "Ediae reported two individuals with early-onset myopia carrying the c.298C>T/p.Arg100* variant in ARR3 in a multi-generational mixed European/Indigenous Canadian family, a mutation previously identified in an unrelated East Asian family, as well as two additional females from different families." (PMID 40134578, 2025). "The non-syndromic ARR3- associated high myopia was identified in the isolated high myopia group." (PMID 39495751, 2024). "From the rating of the mutant, combined with the proband’s clinical symptoms, family history, and other examination results, we finally inferred that ARR3 mutation (c.666delC, p.Asn222LysfsTer22) might be the cause of the proband’s high myopia." (PMID 36769483, 2023). "We present a hypothesis that higher visual contrast due to the mosaic of mutated ARR3 expression in cones contributes to the development of myopia in female carriers." (PMID 37268727, 2023). "Here, we report a long-term follow-up study of a multigeneration family with a new ARR3 causal mutation, identifying eoHM phenotype in seven affected females, late-onset high myopia in one affected male, and protan/deutan color vision defect in seven individuals of both genders." (PMID 37268727, 2023). "However, using exome sequencing (ES), we identified the first high myopia case with hemizygous ARR3-related mutation in a male patient in a Southern Chinese family." (PMID 34966409, 2021). "ARR3 has been associated with X-linked, female-limited, high myopia." (PMID 34966409, 2021). "Therefore, an in-depth investigation into the role of the ARR3 gene in myopia, particularly its high frequency and unique X-linked female-limited inheritance pattern, is crucial for elucidating the pathogenesis of myopia." (PMID 40134578, 2025). "It remains unclear how pathogenic variants in ARR3 lead to myopia." (PMID 40134578, 2025). "Furthermore, the mutation in ARR3 gene might be responsible for female-limited early onset high myopia." (PMID 37268727, 2023). "Given the multifaceted role of ARR3 in both visual signaling and circadian regulation, further investigation is needed to fully understand its impact on myopia progression." (PMID 40134578, 2025). "This article will review the latest progress in research on the ARR3 gene in myopia, summarize its role in disease mechanisms, and explore future research directions." (PMID 40134578, 2025). "In conclusion, the investigation of ARR3 and its multifaceted role in myopia highlights the need for continued research into the genetic and molecular underpinnings of this condition." (PMID 40134578, 2025). "Given the unique inheritance pattern of ARR3 and its critical role in phototransduction, this gene holds significant value for further investigation in understanding the pathogenesis of myopia, particularly early-onset high myopia." (PMID 40134578, 2025).
myopia (continued). "The other two examples are PCDH19-related neurodevelopmental disorder (MIM #300088) and ARR3-related early-onset high myopia (MIM #301010)." (PMID 40490530, 2025). "We emphasize the necessity for further studies to elucidate the role of ARR3 in myopia, particularly regarding its impact on visual development and the genetic predisposition observed in specific populations." (PMID 40134578, 2025). "In conclusion, our study enriched our knowledge regarding eoHM, especially ARR3-associated MYP26 with cone involvement, which develops into pathologic myopia with age." (PMID 36180177, 2023). "X-linked myopia 26 (Myopia 26, MIM #301010), which is caused by the variants of ARR3 (MIM *301770), is characterized by female-limited early-onset high myopia (eo-HM)." (PMID 36769483, 2023). "Causal pathogenic variants in ARR3 were present in 5% of our patients undergoing WES with vision panel and therefore it is a relatively common cause of high myopia." (PMID 35001458, 2022). "Identification of the inheritance pattern during first presentation by drawing a family pedigree will increase early recognition of this type of myopia and as a consequence will lead to diagnosing ARR3, improve genetic counseling and treatment initiation." (PMID 35001458, 2022). "Meanwhile, male family members carrying the pathogenic ARR3 mutation present with astigmatism and mild myopia but do not exhibit eoHM, show a later age of onset, or display no myopia phenotype at all." (PMID 40134578, 2025). "This pattern was consistently observed in two additional family members who also carried the ARR3 mutation, each displaying mild phenotypes without the hallmark early-onset of high myopia." (PMID 40134578, 2025). "Variants in ARR3 (the X‐linked gene encoding cone arrestin) lead to high myopia in females rather than males." (PMID 40013354, 2025). "Notably, eoHM was observed in all female family members carrying the ARR3 variant, including the young individual III1, who exhibited a high degree of myopia at −7.25/−7.75 diopters with axial length measuring 24.62/24.60 mm." (PMID 38517428, 2024). "The present results, on one hand, confirmed that high myopia is associated with reduced amplitudes of the DA a-wave, regardless of the presence of ARR3 gene mutation." (PMID 39420435, 2024). "A similar mechanism may apply to the genes linked to myopia, such as MYP1, ARR3, which are located on the X chromosome, suggesting a parallel between the genetic determinants of height and myopia." (PMID 38654225, 2024). "So in addition to ocular mechanisms, defects in ARR3 could also provoke a systemic melatonin‐driven signal leading to myopia." (PMID 35001458, 2022). "We advise to include the ARR3 gene to existing WES analysis panels for myopia." (PMID 35001458, 2022). "Two previous reports described the link between ARR3 and early onset high myopia." (PMID 35001458, 2022). "This experimental dataset allows us to formulate two reasonable, albeit incomplete hypotheses on the pathogenesis of myopia in ARR3-mutant patients." (PMID 33482870, 2021). "In the context of myopia, however, ARR3’s role in phototransduction in cone cells could increase photosensitivity and enhance contrast differences, potentially creating retinal image disparities that promote myopia development." (PMID 40134578, 2025). "Additionally, 150 unrelated female patients with a phenotype of high myopia were screened and c.228T>A p.Tyr76* and other pathogenic variants in the ARR3 gene were absent in the sporadic cases." (PMID 37268727, 2023). "In addition, this study not only enhanced the correlation between ARR3 and early-onset high myopia but also provided explanations for different phenotypes, which may inspire follow-up studies." (PMID 36769483, 2023). "The ARR3 gene (cone arrestin, OMIM: 301770) has gained significant attention as a pivotal factor in the etiology of myopia, particularly early-onset high myopia (eoHM)." (PMID 40134578, 2025).
myopia (continued). "This could be viewed as if ARR3-linked cone dysfunction only led to myopia if an additional condition, the functional heterogeneity of L/M cones was also granted, explaining why such mutations cause myopia in heterozygous females, but not in hemizygous males." (PMID 39420435, 2024). "Consistent with these ARR3-mutation reports, eoHM was a female-limited manifestation in our pedigree (IV-10, a male mutation carrier, had a history of myopia since Grade 6 in primary school, developing to high myopia in middle school, so was not classified as eoHM)." (PMID 37268727, 2023). "This novel truncated mutation (ARR3: c.569C>G, p.S190*) co-segregated with the disease phenotype in affected family members and demonstrated that high myopia caused by ARR3 is not X-linked, female-limited, where a complicated X-linked inheritance pattern may exist." (PMID 34966409, 2021). "Here, we present our hypothesis based on the relationship between myopia and visional contrast, and the possible pattern of X-chromosome inactivation (XCI) of ARR3." (PMID 37268727, 2023). "Myopia is a prominent feature of some of the disorders, including blue cone monochromacy, Bornholm eye disease, PDE6‐associated achromatopsia (but not achromatopsia associated with CNGA3 or CNGB3) and ARR3‐associated disease (in females)." (PMID 40013354, 2025). "Although retinal alterations have been largely reported in myopia in general, and age-related cone dysfunction was demonstrated for ARR3 knockout mice in a murine model, the latter could not unambiguously be evidenced in humans." (PMID 39420435, 2024).
retinoblastoma (11 papers, 2020 to 2025). A malignant tumor that originates in the nuclear layer of the retina. "Subtype 1 retinoblastoma likely arise from cone as it usually has a higher expression of cone markers and Photoreceptor genes (such as ARR3 and GUCA1B)." (PMID 37777551, 2023). "Our data indicate that the tumor cells in Rb organoids expressed ARR3 and Ki67, consistent with the cone origin of human retinoblastoma." (PMID 36714839, 2022). "Subseqeunt studies supported the notion that ARR3-positive maturing cone photoreceptor cells are especially sensitive to loss of RB1 expression, reacting with re-entry into cell cycle and development of retinoblastoma." (PMID 35565295, 2022). "To explore further the heterogeneity in terms of cone differentiation in retinoblastoma, we studied by immunohistochemistry the distribution of an early photoreceptor marker (CRX), and a later marker specific to the cone lineage (ARR3)." (PMID 34552068, 2021). "It has been reported that RB loss induces cell cycle entry in immature (ARR3−) but not in maturing (ARR3+) cone precursors, as cone precursors were uniquely sensitive to RB depletion in retinoblastoma cells." (PMID 34815392, 2021). "Furthermore, pRb-depleted human cone cells that express medium/long-wave-sensitive (M/L) opsin and cone arrestin (ARR3) form retinoma and retinoblastoma-like lesions." (PMID 32824373, 2020).
cone dystrophy (4 papers, 2021 to 2025). An inherited ocular disorder characterized by the loss of cone cells, the photoreceptors responsible for both central and color vision. "For example, an age related cone dystrophy was suggested in Arr4−/− mice (Arr4 being the murine orthologue of ARR3) based on immune-histochemical findings and the pronounced diminishment in photopic flash and flicker ERGs." (PMID 33482870, 2021). "The cone involvement in ERG of patients with MYP26 and the strong association between the underlying pathogenic mechanism of ARR3 and cones suggested that ARR3-associated MYP26 and cone dystrophy are distinct but not completely separate." (PMID 36180177, 2023). "Without normal ARR3 expression, cone photoreceptors slowly degenerate with increasing age, making this a valuable model for studying age-related cone dystrophy." (PMID 40134578, 2025). "No characteristics of cone dystrophy - expected based on results of the murine ARR3 knockout model were observed." (PMID 39420435, 2024).